VEGFC (vascular endothelial growth factor C)
Diseases named in the same sentence as VEGFC in open-access papers (continued):
Sharing a sentence is not in itself a finding about the gene and the disease.
tumor (continued). "Ligand VEGFC (a positive regulation signaling of lymph angiogenesis) could interact with receptor FLT4 to upregulate target gene TGFB1, which is a tumor promoter in this carcinogenic progression to induce cancer cell proliferation, migration and EMT." (PMID 31126066, 2019). "The following has been reported: (i) VEGFR3 and its ligand, VEGFC, are responsible for lymphangiogenesis; (ii) VEGFC and VEGFD contribute to tumor angiogenesis by binding to VEGFR2 and VEGFR3; (iii) VEGFR3 is expressed in the tip cells of tumor vessels." (PMID 30845711, 2019). "Furthermore, we demonstrated that miR-548k modulating the tumor microenvironment by promoting VEGFC secretion and stimulating lymphangiogenesis through ADAMTS1/VEGFC/VEGFR3 pathways, while promoting metastasis by regulating KLF10/EGFR axis." (PMID 30131072, 2018). "Triple-negative disease often has significantly higher levels of VEGFC secretion in the tumor microenvironment, as well as increased lymphatic vessel density and lymphovascular invasion, when compared to receptor-positive subtypes." (PMID 29976154, 2018). "We also investigated how the BRG1's regulation of the tumor-induced lymphangiogenesis depended on STAT3 and VEGFC, which is a mechanism that could be blocked by STAT3 inhibitor or the VEGFC antibody." (PMID 27145366, 2016). "Moreover, our data also indicate that VEGFC, VCAM and FOXC were upregulated with nuclear TEF3-1 overexpression in HUVECs, these genes are all involved in angiogenesis, promoting vascular and tumor growth." (PMID 26885617, 2016). "In angiogenesis, DUSP1/MKP1 expression is associated with increased invasiveness of NSCLC due to an increased expression of VEGFC, suggesting that DUSP1 inhibition could be a good strategy to inhibit tumor invasion and angiogenesis." (PMID 24886454, 2014). "For example, KDR expression by itself was not significantly altered between tumor and normal samples, but co-expression of KDR with VEGFC, NRP1, and PLXNC1 was associated with tumors." (PMID 23667446, 2013). "The few macrophages present in the TGFα-negative tumors in our study did not express VEGFC, but they did so when tumor cells were transfected with TGFα transgenes and then implanted into the cecal walls of mice." (PMID 23986907, 2013). "Peritumoral lymphangiogenesis involves the secretion of specific glycoproteins designated vascular endothelial growth factor C (VEGF-C) and (VEGF-D) that act on lymphatic endothelium, and are components of an established signaling system for tumor lymphangiogenesis." (PMID 20652010, 2010). "Similarly, the VEGFC protein content, although not significant at the chosen alpha of 0.05, clusters with the percentage change in tumor volume using correlation analysis." (PMID 39998766, 2025). "Additionally, compared with normal mice, tumor-bearing mice presented substantially higher levels of VEGFA (22.3 versus 16.4 pg/mL), VEGFC (40.3 versus 31.3 pg/mL), and VEGFD (43.5 versus 33.4 pg/mL) in the peripheral blood, indicating that these factors were secreted into the TDLN." (PMID 40693467, 2025). "VEGFC overexpression in tumors induces a stronger immune response followed by the application of anti-PD-1 or anti-CTLA-4 treatment, in which the tumors displayed decreased tumor volumes and tumor weight and showed longer survival compared to the Vector group in the mice." (PMID 37790751, 2023). "The result suggests that mTOR and c‐Myc, but not VEGFC, were involved in tumor growth." (PMID 33128283, 2021). "The tumor growth in QGP‐1 xenograft mice with c‐Myc overexpression could be suppressed by RAD001 or the c‐Myc inhibitor alone but not by the VEGFC‐neutralizing recombinant protein." (PMID 33128283, 2021). "In addition to immune suppressive functions, HLA-G/ILTs can promote intratumor vascular remodeling by enhancing vascular endothelial growth factor-C (VEGF-C) expression, and increase tumor metastasis by inducing cancer promoting factor matrix metalloproteinases (MMPs) expression." (PMID 34276691, 2021).
tumor (continued). "Vascular endothelial growth factor C (VEGFC), through binding to its receptor VEGFR3 on lymphatic endothelial cells (LECs), promotes LEC proliferation and migration, resulting in hyperplasia, dilation and increased permeability of lymphatic vessels in the tumor microenvironment 5-7." (PMID 32089745, 2020). "The in vivo tumor growth experiments were then correlated with the in vitro measurements of cell proliferation, thus confirming that the effects of VEGFC or of the absence of VEGFC may principally consist in an autocrine or paracrine effect on tumor cells." (PMID 33067561, 2020). "Collectively, our results reveal that overexpression miR-548k may promote lymphangiogensis and lymphatic metastasis of ESCC through modulating the conversation between tumor cells and lymphatic endothelial cells in tumor microenvironment via ADAMTS1/VEGFC/VEGFR3 cascade." (PMID 30131072, 2018). "Therefore, it is reasonable to suppose that AnnexinA7 through the coordination of VEGFC/D-VEGFR3/NRP2, and SDF1/CXCR4 may affect the process of tumor development and progression." (PMID 29783989, 2018). "This suggests that while macrophages may act through an autocrine mechanism to increase macrophage VEGFC synthesis, this may not be the main source of stromal VEGFC in tumours of stressed individuals." (PMID 26925549, 2016). "Importantly, downregulation of WISP1 in vivo also induced decrease in expression of ICAM-1, VCAM-1, VEGFC, MMP-2, MMP-9 and increase in E-cadherin, suggesting that WISP1 downregulation not only inhibited tumor growth but also suppressed tumor metastasis in vivo." (PMID 27409174, 2016). "For instance, the direct involvement in tumor progression and metastasis has been demonstrated for insulin-like growth factor 1 (IGF-1) and its receptor (IGF-1R), transforming growth factor β (TGF-β), vascular endothelial growth factor C (VEGF-C), and matrix metalloproteinases (MMPs)." (PMID 23409034, 2013). "Apart from its pro-apoptotic, growth inhibitory, and anti-angiogenic properties, this could be, at least in part, due to downregulating tumour progression and invasion-related genes (u-PAR, HIF1α, and VEGFC) and upregulating NSCLC tumour-related suppressor genes (FHIT, RASSF1, and VHL) by Enz." (PMID 20736951, 2010). "Lymphatic survival and remodeling from H-FIRE treatment, although not likely dependent on VEGFC at the time scale and tissue level observed in this study, could contribute to the understanding of previous work through the measurement of tumor drainage following H-FIRE application." (PMID 39998766, 2025). "Interestingly, VEGFC showed no cell‐type‐specific expression across tumor cells and CAFs." (PMID 40843133, 2025). "Furthermore, the recent finding that the VEGFC may negatively regulate the metastatic properties of MB would suggest that not all the factors involved show a pro-tumor effect." (PMID 40677711, 2025). "However, VEGFC was thought to play a major role in lymphangiogenesis but not tumour angiogenesis." (PMID 30584257, 2018). "In addition, we detected VEGFC in the tumor microenvironment in vivo but not in 4T1 cells in vitro." (PMID 24589997, 2014). "Furthermore, we demonstrated that tumor-secreted VEGFA induced lymphangiogenesis in TDLNs to promote premetastatic niche (PMN) formation; VEGFC promoted HEV proliferation but did not affect its lymphocyte homing function." (PMID 40693467, 2025). "Interestingly, when compared to their individual tumor of origin and not as a cohort, primary cell cultures displayed an even slightly higher mRNA expression of CA9 and HIF1A, while the expression of VHL, VEGFA and VEGFC remained constant." (PMID 35646693, 2022).
cancer (444 papers, 2001 to 2026). A tumor composed of atypical neoplastic, often pleomorphic cells that invade other tissues. "The overexpression of VEGFC in tumors has been associated with lymphatic proliferation and enlargement, increments in metastases, and worse prognosis in cancers such as melanoma, breast, colorectal, and gastric cancer." (PMID 41459512, 2025). "Cancer-associated fibroblasts (CAFs) also contribute to lymphatic vessel proliferation and permeability through the secretion of VEGFC and other lymphangiogenic factors." (PMID 36612017, 2022). "Our results, consistent with the previous studies, indicated that CD276, IL1B, LYVE1 and VEGFC are associated with cancer progression." (PMID 33995379, 2021). "We observed that VEGFC was associated with poor prognosis across multiple cancers." (PMID 37852616, 2023). "Thus, elucidating the molecular mechanisms underlying VEGFC expression modulation in cancer cells is of great significance." (PMID 35600335, 2022). "Furthermore, VEGFC can be translocated to cell nuclear causing cancer cell proliferation and lymphangiogenesis through the promotion by MIR27A." (PMID 31126066, 2019). "Of note, here we figured out that miR-548k was associated with VEGFC regulation and previous studies also demonstrated that serum VEGFC could serve as a possible diagnostic marker for some cancers." (PMID 30131072, 2018). "Vascular Endothelial Growth Factor C (VEGF-C) has critical roles in angiogenesis in human cancers; however, the underlying mechanisms regulating VEGF-C expression remain largely unknown." (PMID 26460960, 2015). "Spatial transcriptomic and immunostaining analyses confirmed cancer-associated fibroblast (CAF)-LEC proximity and vascular endothelial growth factor-C (VEGF-C) localization within CAFs, supporting a CAF-dependent lymphangiogenic route." (PMID 42107070, 2026). "For instance, recent studies have demonstrated that enhanced VEGFC secretion promotes lymphangiogenesis and lymph node metastasis in various cancers, such as bladder cancer." (PMID 41333209, 2025). "Malignant tumors release growth factors like vascular endothelial growth factor C (VEGF‐C), promoting the expansion of lymphatic vessels (lymphangiogenesis) in primary tumors and draining sentinel lymph nodes, facilitating lymph node metastasis." (PMID 39791369, 2025). "For instance, the cancer vaccine VEGFC-vax overexpresses VEGFC and when administered locally can promote an antitumor T cell response." (PMID 39880866, 2025). "Cancer biomarkers include substances like carcinoembryonic antigen (CEA) and vascular endothelial growth factor-C (VEGF-C), which indicate cancer progression and patient survival rates." (PMID 41227463, 2025). "Several findings have supported the role of the RTK FMS-Related Tyrosine Kinase 4, FLT4, also called VEGFR3 (Vascular Endothelial Growth Factor Receptor- 3) and its ligand, VEGFC (Vascular Endothelial Growth Factor-C), in cancer progression." (PMID 40316529, 2025). "Several factors were shown to promote lymphangiogenesis in cancer, among which vascular endothelial growth factor C (VEGF-C) is the most prominent and extensively studied lymphangiogenic factor." (PMID 39664183, 2024). "VEGFC-dependent activation of VEGFR-3 in colorectal TAMs weakened antitumor adaptive immunity promoting cancer immune escape; these effects were abolished upon VEGFR-3 inhibition." (PMID 38464522, 2024). "An IgG-like fusion protein molecule (VEGF receptor 31-immunoglobulin, VEGFR31-Ig) binding VEGFC has been developed to inhibit lymphangiogenesis, thereby suppressing cancer growth and metastasis." (PMID 38172098, 2024). "The EVs of the two complex carcinoma cell lines shared 487 over-represented proteins, mostly associated with angiogenesis, cell migration, adhesion and motility (ECM1, EDIL3, VEGFC)." (PMID 39462388, 2024). "VEGFC acts as the upstream of YAP1 in amplification to increase lymphatic density in some malignant tumors." (PMID 37974224, 2023).
cancer (continued). "Although VEGFC is known to be mainly associated with the growth of lymphatic vessels during lymphangiogenesis, it could indirectly influence perineural invasion, since as cancer cells spread through the lymphatic system, they could encounter nerves and infiltrate the perineural space." (PMID 38203550, 2023). "As a key regulator of angiogenesis in cancer, VEGFC can be activated by oncogenes, growth factors, and stress, such as hypoxia." (PMID 36902193, 2023). "Notable positive associations between stromal, immune, and ESTIMATE scores and VEGFC were observed in most cancers." (PMID 37852616, 2023). "Here, the cancer-inducing property of LPS has been demonstrated by the increase of VEGFC expression (18%) and secretion (40%) from SW480 cells, whereas its inductions were inhibited after adding EIF or CGA in a dose-dependent action." (PMID 37509740, 2023). "KRAS-mut cancers conserved VEGFC, an activator of lymphangiogenesis and immunomodulator associated with poor prognosis in LUAD." (PMID 36612014, 2022). "Ectonucleoside triphosphate diphosphohydrolase 1 (ENTPD1) is positively correlated with LYVE1, PDPN, and VEGFC in the LECs of patients with different cancers." (PMID 36067135, 2022). "Vascular endothelial growth factor C (VEGFC) has been demonstrated to accelerate cancer metastasis and modulate the immune system by enhancing lymphangiogenesis." (PMID 35600335, 2022). "We observed that LNMAS exerted an inhibitory effect on lymphangiogenesis in vitro and in vivo by reducing VEGFC derived from cancer cells." (PMID 35152264, 2022). "Targeting the VEGFC/VEGFR3 pathway in combination with immunotherapy is being considered as a candidate strategy for treating cancer." (PMID 36612017, 2022). "Accordingly, specific inhibition of JUN in fibroblasts successfully suppresses CAF functions, for example, VEGFC expression and secretion, and thereby curbs cancer development." (PMID 36438487, 2022). "Vascular endothelial growth factor C (VEGFC) and multiple chemokines induce and accelerate metastatic cancer cells entry into lymphatic vessels, promoting metastatic spread." (PMID 35530337, 2022). "Overexpression of VEGFC in mouse lungs elevates the lymphatic vessel density and contributes to the spread of cancer cells from the lung to other regions." (PMID 35530337, 2022). "Cancer cell-secreted VEGFC regulated by ZKSCAN5 controls HLEC proliferation, migration, and tube formation." (PMID 35600335, 2022). "VEGFC stimulates the formation of new lymph vessels and provides a route for detached cancer cells to metastasise to distant sites." (PMID 35600335, 2022). "Cancer cell-secreted VEGFC markedly enhanced the proliferation and migration of lymphocyte endothelial cells." (PMID 35600335, 2022). "Crucial functions of VEGFC enhance cancer cell mobility and increase invasion capabilities in solid tumours, consequently, promoting cancer cell metastasis to distant sites through lymphangiogenesis." (PMID 36412907, 2022). "VEGFC and various chemokines promote the migration of cancer cells into lymphatic vessels, facilitating metastatic spread." (PMID 34649956, 2021). "In addition, oxidised low-density lipoprotein (oxLDL) is a risk factor in the pathogenesis of cancers linked to its roles in abnormal lipid metabolism, and has been shown to promote lymphatic metastasis of GC via the up-regulated expression and secretion of VEGFC." (PMID 33407483, 2021). "VEGFC was shown to increase neogenesis of lymphatic vessels with increased permeability and higher number of infiltrating cancer cells." (PMID 34568423, 2021). "Genes such are GSTA4, GSTO2, KLK3, PGF were down-regulated and E2F2, MMP9, PIM2, VEGFC are up-regulated in all cancer nodules." (PMID 34209090, 2021). "Among all proangiogenic factors, vascular endothelial growth factor C (VEGF-C) is a critical lymphangiogenic inducer in human cancers, including oral SCC." (PMID 33668218, 2021).
cancer (continued). "In colorectal cancer, the VEGFC/VEGFR3 axis was shown to be upregulated in human primary cancers and to contribute to metastasis and disease progression on multiple levels." (PMID 34568423, 2021). "The lymphatic system is one of the main routes of distant metastasis and growth of cancer cells, among which vascular endothelial growth factor C (VEGF-C) is currently regarded as the most representative lymphangiogenic factor." (PMID 34026612, 2021). "When VEGFC is overexpressed in mouse lungs, it increases lymphatic vessel density, increasing the spread of cancer cells from the lung to other organs." (PMID 34649956, 2021). "Hence, BACH1 and VEGFC may serve as candidate diagnostic biomarkers in cancer patients." (PMID 32132179, 2020). "VEGFC proteolytic processing and HLEC tube formation were inhibited by TGF-β and partially rescued by CCBE1 overexpression in SW837 cells and cancer-associated fibroblasts (CAFs)." (PMID 32089745, 2020). "The results of previous studies suggest that VEGFC acts as an oncogene to promote the proliferation, metastasis and angiogenesis in cancers." (PMID 32342645, 2020). "Altogether, our results uncover a novel role for the BACH/VEGFC signaling axis in lymphatic formation during embryogenesis and cancer, providing a novel potential target for therapeutic interventions." (PMID 32132179, 2020). "AG-1031 treated A549 cells and tumors from AG-1031 treated animals showed a significant decrease in the levels of both PC4 and VEGFC, a key mediator of angiogenesis in cancer." (PMID 32231397, 2020). "Several of these genes are involved in pathways that define the hallmarks of cancer, such as VEGFC (lymphangiogenesis), CASP2 (apoptosis and cell stress), and CDC20 (cellular proliferation)." (PMID 30866919, 2019). "VEGFC, the primary mediator of lymphangiogenesis in cancers, has been overexpressed in a number of models leading to increased lymphatics." (PMID 29976154, 2018). "As miR-27b is lost in cancer cells, VEGFC expression increases, resulting in increased metastatic potential." (PMID 30328349, 2018). "Previous studies using various transgenic mouse models employing vascular endothelial growth factor C/D (VEGF-C/D) overexpression or VEGF-C/D trap suggested a potential role for lymphangiogenesis in cancer progression." (PMID 30592710, 2018). "It has been well established that LECs stimulated by VEGFC undergo a number of activating cellular changes that can be hijacked by cancer cells to facilitate invasion." (PMID 29976154, 2018). "Expression of VEGFB mRNA was significantly reduced by 2.5-fold in primary AECII derived from cancers as compared to cells derived from normal lungs and VEGFC expression was downregulated in cultured AECII (p value at 0.056)." (PMID 29137669, 2017). "Vascular endothelial growth factor-C (VEGF-C) has been implicated in lymphangiogenesis and is correlated with cancer metastasis." (PMID 26824419, 2016). "Cancer cell can release the VEGFC and VEGF-D, which are the specific lymphangiogenesis factors identified." (PMID 27145366, 2016). "They include APOA1, VEGFC, YWHAZ, B2M, EIF2S1, CCR9 and many other genes that have been associated with the hallmarks of cancer." (PMID 25986937, 2015). "On the other hand the VEGFC/VEGF-R3 pathway has been also demonstrated relevant for hematogenous cancer dissemination as well." (PMID 22808003, 2012). "Mutations in genes that regulate VEGFC or its receptors (such as VEGFR-3) might also impact its function and contribute to cancer progression." (PMID 39328205, 2024). "During the formation of cSCC, on the one hand, YAP1 combined with VEGFC to promote lymphatic development and generate anti-cancer cells, and on the other hand, it may combine with TAZ to promote the proliferation of cSCC cells." (PMID 37974224, 2023). "We speculated that the balanced of Piezo1-YAP1/VEGFC in preserving the lymphatic density and drainage function might be beneficial to prevent cancer progression." (PMID 37974224, 2023).